INVS (inversin)
Description:
Required for normal renal development and establishment of left-right axis. Probably acts as a molecular switch between different Wnt signaling pathways. Inhibits the canonical Wnt pathway by targeting cytoplasmic disheveled (DVL1) for degradation by the ubiquitin-proteasome. This suggests that it is required in renal development to oppose the repression of terminal differentiation of tubular epithelial cells by Wnt signaling. Involved in the organization of apical junctions in kidney cells together with NPHP1, NPHP4 and RPGRIP1L/NPHP8 (By similarity). Does not seem to be strictly required for ciliogenesis (By similarity).
Synonyms: INV; NPHP2; NPH2
Tractability: Antibody: UniProt places it where antibodies can reach, with medium confidence. PROTAC: UniProt records ubiquitination sites on it; ubiquitination databases record sites on it.
Gene: Protein-coding gene on chromosome 9 (100,098,699 to 100,306,072, forward strand). Ensembl gene ENSG00000119509.
Subcellular location: Cytoplasm; Cytoplasm, cytoskeleton; Cytoplasm, cytoskeleton, spindle; Membrane; Nucleus; Cell projection, cilium
Subcellular location (Human Protein Atlas): Cytosol; Primary cilium; Basal body; Centrosome
Gene Ontology:
Molecular function: protein binding
Biological process: negative regulation of canonical Wnt signaling pathway; kidney development; protein localization to ciliary inversin compartment
Cellular component: cilium; cytoplasm; cytoskeleton; membrane; nucleus; spindle
Genetic constraint (gnomAD): Loss-of-function variants: 80 observed, 102.35 expected, observed/expected ratio (o/e) 0.78, 90% interval 0.65 to 0.94. The upper end of that interval is the gene's LOEUF score, 0.94, which puts it in group 3 of 6, group 1 being the genes least tolerant of losing a copy. Missense variants: 1,086 observed, 1,292.2 expected, observed/expected ratio (o/e) 0.84, 90% interval 0.8 to 0.88. Synonymous variants: 433 observed, 476.43 expected, observed/expected ratio (o/e) 0.91, 90% interval 0.84 to 0.98.
Gene-disease validity (ClinGen):
ClinGen rates the evidence that INVS causes each of these diseases.
nephronophthisis 2 (autosomal recessive): Definitive. Any nephronophthisis in which the cause of the disease is a mutation in the INVS gene.
Homologues: Orthologues: chimpanzee INVS (99% identical), macaque INVS (98% identical), dog INVS (89% identical), rabbit INVS (88% identical), pig INVS (87% identical), guinea pig INVS (86% identical), rat Invs (81% identical), mouse Invs (81% identical), zebrafish invs (53% identical), tropical clawed frog invs (48% identical), Caenorhabditis elegans mlt-4 (17% identical).
Diseases named in the same sentence as INVS in open-access papers:
INVS is named in the same sentence as 59 diseases in open-access papers, as found by Europe PMC text mining. Sharing a sentence is not in itself a finding about the gene and the disease. The quoted sentences say what the papers report.
nephronophthisis (13 papers, 2013 to 2025). Progressive tubulointerstitial injury, inherited in an autosomal recessive pattern, caused by mutations in genes involved in ciliary function, which may result in an end stage renal failure. "The ciliopathy nephronophthisis has been associated with a mutation in INVS/NPHP2 that also affects motile cilia." (PMID 38674609, 2024). "In our cohort, INVS loss was detected, which caused nephronophthisis." (PMID 37535131, 2024). "Previous research in mice showed that blocking the gene for a protein called INVS recreated signs similar to nephronophthisis." (PMID 36920028, 2023). "More recently, localisation of ANKS6 to the primary cilium and interactions between ANKS6 and proteins involved in nephronophthisis (INVS, NHPH3, NEK8) were demonstrated." (PMID 26327442, 2015). "In this case, sequencing and MLPA analysis of NPHP1 was also performed, together with the sequence analysis of other rarer genes related to nephronophthisis (INVS, NPHP3, NPHP4, IQCB1): no pathogenic variant was found in these genes." (PMID 37372410, 2023). "The function of this compartment is poorly understood, but human or mouse mutations in genes encoding components of the INVS compartment, INVS/NPHP2, NPHP3 and ANKS6/NPHP16, are known to lead to infantile nephronophthisis with cystic kidneys, congenital heart defects and laterality defects." (PMID 26967905, 2016). "Mutation in INVS is usually involved in infantile nephronophthisis, but whether it leads to infertility has not yet been reported." (PMID 36437957, 2022). "Likewise, it is important to monitor whether knockdown of Anks3 interaction partners, such as INVS, results in similar metabolic phenotypes in order to improve the understanding of nephronophthisis on metabolic level." (PMID 29899363, 2018).
ciliopathy (6 papers, 2013 to 2024). A genetic disorder of the cellular cilia or the cilia anchoring structures, the basal bodies, or of ciliary function. "The phosphorylated and activated AKT is also reported to localize at the ciliary base and facilitate the ciliogenesis by phosphorylating the ciliary structural protein Inversin (INVS), which is a causative gene for ciliopathy nephronophthisis type II (NPHP2)." (PMID 36547473, 2022). "Many of the mutations known to cause renal anomalies within the ciliopathy spectrum are associated with proteins localized in the cilia transition zone or inversin compartment." (PMID 29963541, 2018). "Many of these cilia mutations comprise cilia transition zone or inversin compartment components, consistent with the known role of these cilia proteins in a wide variety of ciliopathies." (PMID 29963541, 2018). "These include at least twenty MKS/NPHP/JS-associated proteins concentrated at the TZ, multiple ciliopathy proteins targeted specifically at the BB such as OFD1, and proteins such as NPHP2/INVS confined to a proximal ciliary subdomain called the Inversin compartment." (PMID 24339792, 2013).
polycystic kidney disease (6 papers, 2013 to 2024). A usually autosomal dominant and less frequently autosomal recessive genetic disorder characterized by the presence of numerous cysts in the kidneys leading to end-stage renal failure. "Knockout of VANLG2 and inversin/NPHP2 causes a similar type of polycystic kidney, highlighting the connections between PCP and cilia with a potential novel connection to SLMAP3." (PMID 39417621, 2024). "Three of six fetuses with polycystic kidney disease and extra-renal abnormalities displayed a pathogenic variant (INVS, TP63, CEP290)." (PMID 37535131, 2024). "Mutations of the INVS gene have been linked with polycystic kidney disease (nephronophthisis II), which is an autosomal recessive disorder, through activation of the sonic hedgehog pathway and/or negative regulation of the Wnt pathway." (PMID 34947825, 2021). "This step has been proven to be crucial in cystogenesis, while knockout of inversin in mice leads to polycystic kidney disease." (PMID 33800671, 2021). "Namely, it is known that the consecutive constitutive activation of the canonical Wnt pathway in the absence of INVS leads to abnormal primary cilia and cyst formation, resulting in severe polycystic kidney diseases, MCDK, FSGS, or CNF." (PMID 39596188, 2024).
cyst (5 papers, 2019 to 2024). A sac-like closed membranous structure that may be empty or contain fluid or amorphous material. "Mechanistically, we find that removal of cilia reduces the severity of Invs phenotypes, suggesting that, similar to polycystins, INVS inhibits a cilia-dependent cyst and fibrosis activating pathway." (PMID 36920028, 2023). "Understanding the Inversin compartment could provide critical clues to the molecular mechanisms linking cilia, polycystins, cyst formation, and fibrosis." (PMID 36920028, 2023). "Inversin and β-catenin were also highly expressed in ARPKD cyst-lining epithelia (red arrows), although overall levels of renal expression appeared to be similar to those in normal kidneys." (PMID 30414501, 2019).
Nephronophthisis type 2 (3 papers, 2011 to 2021). "Important insight into the link between cilia/basal bodies and Wnt regulation came from studies by Simons and colleagues demonstrating that inversin (Inv), the protein mutated in Nephronophthisis type 2 (NPHP2), interacts with Dvl targeting it for degradation." (PMID 22131874, 2011). "In agreement with that premise, previous studies disclosed that mutation of the inversin gene could result in nephronophthisis type 2, which is mediated by abnormal DVL-1 expression." (PMID 33800671, 2021).
situs inversus (3 papers, 2013 to 2021). A congenital condition in which there is complete right-to-left reversal of the position of the major thoracic and abdominal organs (that is, they are arranged in a mirror image of the normal positioning). "Indeed, mutations in genes encoding other components of the INVS compartment (INVS/NPHP2, NPHP3 and ANKS6/NPHP16) are known to lead to infantile NPH associated with enlarged cystic kidneys or to kidney cystic dysplasia associated with congenital heart defects and situs inversus." (PMID 26967905, 2016). "NPHP type 2, resulting in the rare, yet clinically significant infantile NPHP (with or without situs inversus), is caused due to mutations in the INVS gene (9q21–22) encoding inversin." (PMID 34828368, 2021).
cystic kidney disease (2 papers, 2023 to 2024). A congenital or acquired kidney disorder characterized by the presence of renal cysts. "Mutations in INVS cause nephronophthisis type II (an autosomal recessive cystic kidney disease characterized by extensive renal cysts, situs inversus, and renal failure)." (PMID 39596188, 2024). "Diversin, a switch molecule with structural similarity to inversin, treats renal cysts in zebrafish induced by inversin depletion, indicating that suppression of canonical Wnt signaling is required for successful renal development." (PMID 37238991, 2023).
kidney damage (2 papers, 2017 to 2021). "It is noteworthy that four of six affected individuals presented also with a renal phenotype of early-onset nephropathy with features of tubulo-interstitial nephritis, hypertension and tendency for hyperkalemia, as described for NPHP2 (inversin) mutations." (PMID 28334855, 2017). "Therefore, disturbances of α-tubulin, inversin and DVL-1 found in diseased kidneys might be the underlying pathological mechanism and a result of the switch from noncanonical to canonical Wnt pathway in the developing kidney alluding to the switch between reversible to irreversible kidney damage." (PMID 33800671, 2021).
age-related macular degeneration (1 paper, 2025). Age-related loss of vision in the central portion of the retina (macula), secondary to retinal degeneration. "Defects in inversin are associated with left-right asymmetry, nephronophthisis-2, and age-related macular degeneration (AMD)." (PMID 40610430, 2025).
bladder cancer (1 paper, 2021). "The significant downregulation of inversin speculates that it may serve as a potential candidate biomarker for muscle-invasive bladder cancer." (PMID 34947825, 2021). "The concentration levels of the three circulating proteins inversin, gelsolin, and apolipoprotein A1 identified high-grade bladder cancer with an AUC > 0.84 (95% confidence interval 71–98), 0.76 (95% confidence interval 61–92%), and 0.90 (95% confidence interval 82–98), respectively." (PMID 34947825, 2021). "Further analysis is required to clarify the biological significance of inversin in bladder cancer." (PMID 34947825, 2021). "In addition, inversin was also selected for further validation, as this is the first study to report an elevated inversin level in bladder cancer and could serve as novel biomarker for bladder cancer progression." (PMID 34947825, 2021).
chronic kidney disease (1 paper, 2021). Impairment of the renal function secondary to chronic kidney damage persisting for three or more months. "Namely, we propose that disturbed expression patterns of α-tubulin, inversin and DVL-1 proteins might be the underlying cystogenesis process and an abnormal function of primary cilia leading to chronic kidney diseases." (PMID 33800671, 2021). "Our findings of lowered α-tubulin and inversin expression in CNF and FSGS imply inactivity of the noncanonical Wnt pathway, especially as both conditions tend to lead to end-stage renal disease." (PMID 33800671, 2021).
lung carcinoma (1 paper, 2024). "So far, it has been proven that INVS expression is correlated with the malignant phenotype of non-small cell lung cancer due to INVS enhancing the invasiveness of lung cancer cells, and it was identified as a poor prognostic factor." (PMID 39596188, 2024).
metastatic disease (1 paper, 2024). "By using the immunohistochemistry of primary ccRCC, we found in our cohort containing 34 patients with metastatic disease that the expression of INVS was significantly lower in primary tumors in comparison to solid normal tissue." (PMID 39596188, 2024).
renal carcinoma (1 paper, 2024). A carcinoma arising from the epithelium of the renal parenchyma or the renal pelvis. "However, there is a need for further preclinical studies, including overexpressing or silencing INVS and its related genes/proteins in renal cancer cells, applying immunotherapy to establish possible effects depending on the expression of INVS, and performing later clinical studies." (PMID 39596188, 2024).
renal tumor (1 paper, 2024). "In addition, INVS mRNA was found to be present in different types of tumors, including ccRCC tumors, as well as in various cell lines of normal renal cells and renal tumor lines." (PMID 39596188, 2024).
Salmonella Infections (1 paper, 2025). Infections with bacteria of the genus SALMONELLA. "Having uncovered a molecular function of InvS, we finally investigated its pathophysiological relevance in the context of a Salmonella infection." (PMID 41428736, 2025).
Situs inversus totalis (1 paper, 2023). "Some patients with pathogenic variants in INVS have NPHP, situs inversus totalis, and motile cilia dysgenesis." (PMID 36273371, 2023).
Spherocytosis (1 paper, 2022). The presence of erythrocytes that are sphere-shaped. "Mutation of Leu to Arg at position 6 in ANK1 protein is associated with Spherocytosis, while Leu to Ser in INVS impairs its ability to target DVL1 for degradation." (PMID 35056738, 2022).
cancer (4 papers, 2017 to 2024). A tumor composed of atypical neoplastic, often pleomorphic cells that invade other tissues. "Concerning its role as one of the main factors involved in the regulation of the Wnt signaling pathway as well as its importance in renal development and the pathogenesis of different renal pathologies, the biological function of INVS in cancer is starting to be revealed." (PMID 39596188, 2024). "The exact mechanism by which inversin could increase cancer invasion is at its infancy, however, modulating the epithelial–mesenchymal transition (EMT) by impairing E-cadherin expression and upregulating N-cadherin and Vimentin is a possible mechanism." (PMID 34947825, 2021). "However, there have been no studies on the expression and potential role of INVS in other cancer types, including kidney cancer." (PMID 39596188, 2024).
kidney diseases (2 papers, 2017 to 2021). "As far as we are aware, this is a first study that had shown expression and localization of α-tubulin along with inversin and DVL-1 in fetal and postnatal human kidneys, and that had explored the expression of mentioned proteins in kidney diseases, such as MCDK, FSGS and CNF." (PMID 33800671, 2021). "Furthermore, we wanted to explore whether the expression and staining pattern of α-tubulin, inversin and DVL-1 is disturbed in different kidney diseases when compared to healthy control." (PMID 33800671, 2021).
cardiovascular diseases (1 paper, 2017). "There are 20 unique genes within the 9q22.33 locus and three genes (TGFBR1, NR4A3, and INVS) were linked to cardiovascular diseases." (PMID 28710368, 2017).
tumor (1 paper, 2024). "Moreover, we hypothesized the existence of the INVS interactome network of factors, which, in cooperation with INVS, affect the biological and clinical characteristics of this type of tumor and have potential as diagnostic and pharmacological targets." (PMID 39596188, 2024). "The expression of INVS and its interactome partners in ccRCC was correlated with the differentiation of the tumor and metastasis." (PMID 39596188, 2024). "By exploring the data from the TCGA-KIRC using the Xena USCC portal, we found that the INVS mRNA expression in primary tumors is inversely related to the neoplasm histological grade, being the highest in G1 and the lowest in G4 tumors." (PMID 39596188, 2024). "The expression of INVS and its partners was also correlated with tumor leukocyte infiltration and the expression of immune checkpoint genes." (PMID 39596188, 2024). "We found that the expression of inversin was significantly lower in primary tumor tissue, in comparison to solid normal tissue." (PMID 39596188, 2024). "Altogether, these data point to the role of inversin and its interactome partners in the regulation of the tumor microenvironment, with inflammatory infiltration as the main mechanism of their relationship with ccRCC patient survival." (PMID 39596188, 2024). "The aim of this study was to explore the tumor expression of inversin as a potential prognostic factor and/or therapeutic target in ccRCC." (PMID 39596188, 2024). "In order to reveal the mechanism of INVS and its interactome effects on ccRCC pathogenesis and the clinical outcome, we explored the correlation of INVS and its partners with tumor leukocyte infiltration and the expression of immune checkpoint inhibitors, by using TISIDB and GEPIA portals." (PMID 39596188, 2024). "In addition, we hypothesized that the INVS expression might be related to the regulation of tumor leukocyte infiltration, identifying INVS as a potential predictive factor of the response to immunotherapy in ccRCC." (PMID 39596188, 2024). "Therefore, it can be assumed that INVS absence/low expression in ccRCC might have a role in the metastatic potential of tumor cells." (PMID 39596188, 2024). "We assessed the correlation of INVS and genes of interest in its interactome (NPHP3, DVL1, DVL3, and ANKS6) with tumor immune infiltration and expression using different algorithms (XCELL, TIMER, QUANTISEQ, EPIC, CIBERSORT, CIBERSORT-ABS, and MCPCOUNTER) by using GEPIA." (PMID 39596188, 2024). "Finding that the expression of INVS and its interactome partners was not responsive to therapy with immune checkpoint inhibitors in ccRCC (as well as other types of immune-dependent carcinoma) supports their upstream position in the regulation of the inflammatory tumor microenvironment." (PMID 39596188, 2024).
INVS also shares sentences with these, for which no sentence is quoted: Bardet-Biedl syndrome (2 papers); cystic kidneys (2); melanoma (2); retinitis pigmentosa (2); Alport syndrome (1); benign tumors (1); biliary atresia (1); calculus (1); chronic kidney failure (1); Crigler-Najjar syndrome (1); end-stage renal disease (1); focal segmental glomerulosclerosis (1); Hepatic fibrosis (1); homocysteinemia (1); Hyperkalemia (1); Hypertension (1); hypospadias (1); Infantile nephronophthisis (1); infection (1); Infertility (1); Joubert syndrome (1); lipomatosis (1); Lowe syndrome (1); Meckel-Gruber Syndrome (1); Methylmalonic aciduria (1); multicystic dysplastic kidney (1); non-small cell lung carcinoma (1); oral diseases (1); osteoarthritis (1); periodontal diseases (1).
A further 7 diseases each share a sentence with INVS in 1 paper.